RN7SL89P (RNA, 7SL, cytoplasmic 89, pseudogene)
Gene: Miscellaneous RNA gene on chromosome 4 (105,293,664 to 105,293,946, forward strand). Ensembl gene ENSG00000243383.
Homologues: Orthologues: chimpanzee Metazoa_SRP (98% identical). Paralogues in human: RN7SL1 (79% identical), RN7SL3 (79% identical), RN7SL2 (78% identical), RN7SL125P (77% identical), RN7SL679P (77% identical), RN7SL230P (77% identical), RN7SL444P (77% identical), RN7SL478P (77% identical), RN7SL712P (77% identical), RN7SL823P (77% identical), RN7SL431P (76% identical), RN7SL556P (76% identical), and 707 more.